STAT3 (signal transducer and activator of transcription 3)
Diseases named in the same sentence as STAT3 in open-access papers (continued):
Sharing a sentence is not in itself a finding about the gene and the disease.
pulmonary fibrosis (continued). "However, IL-6-STAT3 signaling has been shown to play a central role in murine pulmonary fibrosis models and phosphorylated STAT3 was detected in nuclei of pneumocytes next to fibrotic lesions in the lungs of IPF patients." (PMID 39578767, 2024). "In addition, the JAK2/STAT3 pathway is important for the development of pulmonary fibrosis in Mycobacterium tuberculosis infection." (PMID 39255287, 2024). "Signal transducer and activator of transcription 3 (STAT-3) and zinc finger protein (Gli-2) are pro-fibrotic molecules which are involved in pulmonary fibrosis, and it was found that circRNA-662 and circRNA-949 have sponge like activity against miR-29b which interacts with STAT-3 and Gli-2." (PMID 38321530, 2024). "However, the immunologic consequences of ERα binding to the STAT3 gene in CD4+ T cells of patients with lung fibrosis remain unexplored." (PMID 36899902, 2023). "It was declared that Stat3 promoted pulmonary fibrosis by mediating IL17 and TGF-beta production." (PMID 37511374, 2023). "Stattic, a STAT3 inhibitor, mitigated the lung fibrosis in a mouse model of RA-ILD." (PMID 37833957, 2023). "This investigation along with previous studies exactly demonstrated that CTS might be a potential medication or adjuvant medication for preventing cardiac or lung fibrosis via inhibiting STAT3-dependent signaling pathway." (PMID 36743695, 2023). "Our results suggest that the SHP-1 agonist SC-43, via targeting the CSF1R/STAT3/NFκB pathway in the alveolar macrophages, may hold great potential in pulmonary fibrosis resolution for IPF patients." (PMID 37291088, 2023). "Our results show that JAK1/2 and STAT3 were activated in animal and cell models of pulmonary fibrosis and that baricitinib has therapeutic effects on pulmonary fibrosis by selectively inhibiting JAK1/2, including reducing the collagen deposition and improving pulmonary function in BLM-injured mice." (PMID 36903446, 2023). "Collectively, this study suggests that fibroblast VDR upregulation may be a self-protective response to limit fibroblast proliferation and activation during pulmonary fibrosis by suppressing the JAK1/STAT3/ER stress pathway." (PMID 37627629, 2023). "Moreover, KYP-2047 was able to modulate the JAK2/STAT3 pathway, highly involved in pulmonary fibrosis." (PMID 37626373, 2023). "An aberrant activation of IL6/JAK/STAT3 and tofacitinib gene signatures was found in biopsies from SSc patients and Tofacitinib was reported to be effective in preventing bleomycin-induced skin and lung fibrosis in the animal models." (PMID 36556466, 2022). "In addition, IL-1β also stimulates the release of IL-6, which not only play the pro-inflammatory role, but also aggravates the pulmonary fibrosis by activating STAT3 pathway." (PMID 36733806, 2022). "Type II alveolar epithelial cell injury can be reduced by inhibiting the STAT3 pathway 47, indicating that IL-6 may participate in pulmonary fibrosis through alveolar epithelial cells." (PMID 36147459, 2022). "At the same time, we found that BLM induced abnormal activation of Stat3, while this abnormal activation was decreased in response to NIF, indicating that NIF may inhibit pulmonary fibrosis by blocking abnormal Stat3 activation." (PMID 35172837, 2022). "Similarly, selective JAK2 tyrosine kinase inhibition by fedratinib attenuated TGF-β- and IL-6-induced myofibroblast activation regulated by JAK2/p-STAT3 as well as reduced bleomycin-induced lung fibrosis in mice in vivo." (PMID 35626663, 2022). "Of note, it has been known that STAT3 regulates bleomycin-induced lung fibrosis." (PMID 36055997, 2022). "Our findings suggest that DHM could alleviate pulmonary fibrosis in the mouse model and restrain the differentiation, proliferation, and migration of fibroblasts or myofibroblasts via the STAT3/pSTAT3/GLUT1 signaling pathways." (PMID 35359847, 2022). "An increasing body of evidence recently suggests that PD-1 could also regulate STAT3 in pulmonary fibrosis and sarcoidosis." (PMID 36544757, 2022).
pulmonary fibrosis (continued). "Taken together, these results suggest that STAT3 could be a potential target for eliminating senescent cells, which could induce recovery from lung fibrosis." (PMID 36055997, 2022). "Moreover, nintedanib reduced the number of senescence-associated β-galactosidase-positive senescent cells in parallel with a reduction in STAT3 phosphorylation and ameliorated collagen deposition in a mouse model of bleomycin-induced lung fibrosis." (PMID 36055997, 2022). "Notably, it has been demonstrated that PD-1 signaling is activated via STAT3 on CD4+ T cells and promotes collagen production by fibroblasts in pulmonary fibrosis, indicating the role of STAT3 in immunosuppression and tumor-promoting responses in the TME." (PMID 36010693, 2022). "Our research suggests that DHM could alleviate pulmonary fibrosis in vitro and in vivo via the STAT3/p-STAT3/GLUT1 signaling pathway." (PMID 35359847, 2022). "However, we only researched metformin to attenuate silica-induced lung fibrosis through AMPK-dependent inhibition of STAT3 expression." (PMID 34399790, 2021). "Other peculiar characteristics of STAT3 cover its ability in inactivation of embryonic lethality, reduction of tubulointerstitial and renal lesions, regulation liver progenitor, development of lung fibrosis." (PMID 33446184, 2021). "In addition, STAT3 activation is detected in lung biopsies from patients with idiopathic pulmonary fibrosis and bleomycin (BLM)-induced murine fibrotic lungs." (PMID 33804639, 2021). "Taken together, we speculated that metformin inhibits pulmonary fibrosis by AMPK-regulated STAT3 activation." (PMID 34399790, 2021). "Our results suggest that neutralizing IL-9 may alleviate pulmonary fibrosis by regulating the STAT3 and SMAD2/3 pathways." (PMID 34831433, 2021). "In fact, STAT3 is considered to be a therapeutic target for anti-lung fibrosis." (PMID 33805945, 2021). "Hsp90 stabilizes and activates STAT3, thus may play a crucial role in the progression of lung fibrosis mediated by IL-640." (PMID 33414495, 2021). "Therefore, targeting JAK2/STAT3 signaling has been highlighted as a potential strategy for treating pulmonary fibrosis." (PMID 34361644, 2021). "Moreover, the STAT3 inhibitor S31-201 reversed miR-301a expression in fibroblasts induced by TGF-β and IL-6, thus implying that the activation of miR-301a in pulmonary fibrosis depended on STAT3." (PMID 32585629, 2020). "We were unable to find any reports linking either PTPN2 to silicosis, and it has been reported that IL-6 family of cytokines, which signal through STAT-3, may contribute to lung fibrosis." (PMID 32054021, 2020). "Western blot analysis of lung tissues in BLM-induced lung fibrosis mice showed an increased expression of extracellular matrix proteins, such as fibronectin, and phosphorylation of STAT3 (Tyr705) protein, a downstream mediator of IL-6 signaling, when compared with lung tissues of the control mice." (PMID 31049028, 2019). "Signal transducer and activator of transcription 3 (STAT3), one of the important downstream mediator of TGF-β1 signaling, is reported to be associated with the enhancement of lung biopsies from idiopathic pulmonary fibrosis patients and in mice with fibrotic lungs." (PMID 31341890, 2019). "We have shown that the IL-6 family of cytokines, which signal through STAT3, may also contribute to lung fibrosis mouse models of fibrosis and that pharmacological inhibition of STAT3 decreased fibrosis in these models." (PMID 30081609, 2018). "Thus, inhibition of downstream JAK2 and STAT3 signaling by JSI-124 reduced both pulmonary fibrosis and expression of these mediators in the lung." (PMID 29409529, 2018). "In rats administered JSI-124, a dual inhibitor of p-JAK2/p-STAT3, at a dose of 1 mg/kg/day, bleomycin-induced lung fibrosis was reduced and collagen deposition in the lung was inhibited, as were JAK2 and STAT3 activation and several markers of fibrosis, autophagy, senescence, and anti-apoptosis." (PMID 29409529, 2018).
pulmonary fibrosis (continued). "In pulmonary fibrosis, this unspecificity may even be favorable, since niclosamide co-inhibits several pathways (e.g., STAT3, AKT, and Wnt/β-catenin) which have been shown to contribute to fibrosis development." (PMID 29910813, 2018). "It has also been proposed that Stat3-activated fibroblasts may participate in lung fibrosis, which shares ECM deposition and remodeling as a common feature with AAA." (PMID 28982132, 2017). "Dysregulated SOCS3 activity may STAT3 signal transduction in fibroblasts/myofibroblasts in idiopathic pulmonary fibrosis (IPF)." (PMID 25888222, 2015). "In addition, the abundant localization of phospho-Stat3 in fibrotic areas at the early fibrotic stage of BLM-induced lung injury was in accord with previous reports on lung sections from both mice with lung fibrosis and patients with IPF." (PMID 26289430, 2015). "The potential role of excessive gp130-mediated STAT3 signalling in human IPF prompted us to explore whether reduction of Stat3 could confer a prophylactic protection from lung fibrosis." (PMID 22684844, 2012). "It is therefore tempting to speculate that, for instance, the combined activity of LT and TNF-α, through induction of gp130-activating cytokines, indirectly promotes Stat3 signalling and the excessive matrix production that underpins lung fibrosis." (PMID 22684844, 2012). "Taken together, our research showed that inhibition of S1pr3 ameliorates bleomycin-induced pulmonary fibrosis by reducing macrophage M2 polarization via the PI3K/Akt-Stat3 signaling pathway, indicating that S1pr3 may be a potential target for pulmonary fibrosis treatment." (PMID 40092491, 2025). "Nonetheless, the expression of CSF1R, MRC1, and FN1 exhibited a significant reduction following SC-43 treatment, implying that SC-43 may inhibit the CSF1R/STAT3 signaling pathway and diminish the expression of fibrotic genes within macrophages in vivo during the pulmonary fibrosis progression." (PMID 37291088, 2023). "JAK2, once activated, recruits and phosphorylates STAT3 which dimerizes and translocates into the nucleus where it activates the transcription of several genes involved in the fibrotic response like IL-6 family of cytokines, which signal through STAT3, may also contribute to lung fibrosis." (PMID 37626373, 2023). "In vitro experiments have further revealed that EBI3 may reduce type I collagen expression when co-cultured with fibroblasts and alleviate pulmonary fibrosis induced by bleomycin by suppressing signal transducer and activator of transcription (STAT3) DNA binding." (PMID 37480105, 2023). "Interestingly, the IL-6/STAT3 axis could contribute to an exacerbated immune response and COVID-19 complications such as thrombosis and lung fibrosis." (PMID 35327634, 2022). "Therefore, this evidence suggests that suppression of the TGF-β1 and Stat3 signalling pathways could reduce pulmonary fibrosis by inhibiting fibroblast activation and excessive ECM expression." (PMID 35172837, 2022). "EGFR activation also leads to STAT3 phosphorylation, which can induce inflammatory responses and imbalanced anti-virus adaptive immune responses, inhibit anti-virus interferon responses, and promote M2 macrophage polarization, pulmonary fibrosis, and thrombosis." (PMID 36532549, 2022). "Moreover, inhibition of the STAT3 pathway by the specific small molecule inhibitor C-188-9 has been demonstrated to decrease fibroblast-to-myofibroblast differentiation in vitro and development of pulmonary fibrosis in bleomycin-treated mice in vivo." (PMID 30481203, 2018). "Several observations have indicated that STAT3 may contribute to the progression of lung fibrosis." (PMID 26772733, 2016). "STAT3 activation may be central to mechanism in conditions such as pulmonary fibrosis." (PMID 24381786, 2013). "PFOB-NE enhance pulmonary siRNA delivery, effectively silencing STAT3/CXCR4 and inhibiting lung fibrosis progression." (PMID 41480009, 2026).
pulmonary fibrosis (continued). "Signal transducer and activator of transcription 3 (STAT3) inhibitor (TTI-101): The STAT3 protein is activated in lung fibroblasts and alveolar type II cells (ATII), thereby contributing to lung fibrosis in IPF." (PMID 40226606, 2025). "We conclude that BIC reduces SiO2-induced pulmonary fibrosis by inhibiting the inflammatory fibrotic responses in silicosis via the TGF-β1/SMAD2/3 and JAK2/STAT3 signaling pathways." (PMID 39060930, 2024). "In a bleomycin-induced pulmonary fibrosis mice model, IL-35 activated STAT1 and STAT4, which in turn suppressed DNA enrichment of STAT3 and inhibited the fibrosis process." (PMID 38641226, 2024). "Next, we investigated the effect of IL6 on STAT3 activation, a canonical transcriptional mediator of IL6 downstream signaling and promoter of pulmonary fibrosis." (PMID 38650935, 2024). "MiRNA-21a-5p overexpression promoted lung fibrosis in bleomycin-induced SSc mice, inducing infiltration of cells expressing TNF-α, IL-1β, IL-6, or IL-17, along with STAT3 phosphorylated cells in the lesional skin." (PMID 38561750, 2024). "Inhibition of STAT3 signaling decreased CD90+ fibroblast resistance to astrosporine-induced apoptosis and the response to TGF-β in idiopathic pulmonary fibrosis." (PMID 36747131, 2023). "Because the STAT3 signaling route is a Smad-independent signaling pathway, it can be used to further our understanding of the function of BFC-TA in the management of pulmonary fibrosis." (PMID 38187805, 2023). "At the same time, PD-1 on CD4 + T cells promoted expression of STAT3 in human lung fibroblasts and mediated the production of IL-17A and TGF-β1 to promote pulmonary fibrosis." (PMID 36747131, 2023). "CTS administration by oral gavage in Sprague-Dawley rats effectively attenuated bleomycin-induced lung fibrosis via depressing phosphorylation of SMAD2/3 and STAT3." (PMID 36743695, 2023). "The levels of activated JAK2 and STAT3 were elevated in alveolar type II epithelial cells (ATII) and lung fibroblasts from patients with IPF, in which JAK2 and STAT3 participate in lung fibrosis by dependent and independent mechanisms." (PMID 35120332, 2022). "Recent studies have also confirmed that C-188-9 (a STAT3 inhibitor) and JSI-124 (a dual inhibitor of JAK2 and STAT3) decrease pulmonary fibrosis." (PMID 36055997, 2022). "The results show that the polycation/siRNA/PFOB nanoemulsions are capable of efficiently silencing the expression of STAT3 and inhibiting chemokine receptor CXCR4—two validated targets in pulmonary fibrosis." (PMID 34994102, 2022). "To investigate the signaling pathways pivotal for IL-11–driven pulmonary fibrosis, we assessed the activation status of SMAD2, ERK, and STAT3 by Western blotting of lung homogenates from the PBS-treated group, siIL11@PPGC NP–treated group, or healthy controls." (PMID 35731866, 2022). "STAT3 regulates IL-6- and TGF-β-mediated myofibroblast differentiation and the epithelial-to-mesenchymal transition (EMT) in pulmonary fibrosis." (PMID 36556326, 2022). "The EPs show deep lung penetration and cytosolic siRNA delivery to mediate highly effective pulmonary STAT3 silencing and CXCR4 inhibition in a mouse model of pulmonary fibrosis upon intratracheal administration." (PMID 34994102, 2022). "In an animal model of bleomycin-induced lung fibrosis and PH, p-JAK2/p-STAT3 were overexpressed and localized in pulmonary arteries." (PMID 34067108, 2021). "In this study, we demonstrated the anti-pulmonary-fibrosis and anti-inflammatory effects of Fed through suppressing both JAK2/STAT3 and TGF-β1 signaling." (PMID 34361644, 2021).
pulmonary fibrosis (continued). "In BLM-induced pulmonary fibrosis rats, KX-01 reduced pathological scores, collagen deposition, α-SMA, collagen I, collagen III, p-Src, HIF-1α, and p-STAT3." (PMID 34349652, 2021). "The skeletal muscle tissue isolated from lung injury mice increased the activation of STAT3 and AMPK, accompanied by an increased amount of Atrogin-1 protein in BLM-induced lung fibrosis mice." (PMID 31049028, 2019). "It had been confirmed that the signal transducer and activator of transcription 3 (STAT3) is upregulated in lung fibroblasts and alveolar type II cells (ATII), which subsequently leads to lung fibrosis." (PMID 31379980, 2019). "The signal transducer and activator of transcription 3 (STAT3) protein is activated in lung fibroblasts and alveolar type II cells (ATII), thereby contributing to lung fibrosis in IPF." (PMID 29409529, 2018). "qRT-PCR and Western blot analysis showed that JAK1, STAT3 and ADAM17 levels increased in the pulmonary fibrosis model in vivo, whereas FFK remarkably decreased JAK1, STAT3 and ADAM17 expression." (PMID 30092799, 2018). "To investigate the mechanism by which IL-27 acts in pulmonary fibrosis, we determined JAK, STAT1, STAT3, STAT5, and SOCS3 protein levels as well as STAT1, STAT3, and STAT5 phosphorylation levels using Western blot analysis." (PMID 25888222, 2015). "STAT3 may be involved in pulmonary fibrosis through its role in fibroblast transformation, potentially contributing to the development of ILD in patients with STAT3 GOF." (PMID 40703313, 2025). "In addition, we demonstrated that DST-3 inhibited the levels of p-STAT3 (Tyr705 and Ser727) in C57BL/6 mice with BLM-induced pulmonary fibrosis." (PMID 41155944, 2025). "In menopausal females, the gut microbiome continues to drive lung fibrosis, but due to the reduced estrogen state, there is no inhibition of STAT3 expression and Th17 cell development." (PMID 36899902, 2023). "Because transcription factor ESR-1 (alpha subunit of ESR) was identified as binding to the STAT3 gene in CD4+ T cells, we investigated the role of the ERα subunit in profibrotic cytokine expression using a murine model of bleomycin-induced lung fibrosis in WT and ESR-1 knockout (ESR-1-/-) mice." (PMID 36899902, 2023). "Previous studies have reported the pro-fibrotic activity of JAK2 and STAT3 in pulmonary fibrosis, but the involvement of JAK1 has not been well studied." (PMID 36903446, 2023). "In this study, we found that NIF may regulate the TGF-β/Smad and Stat3 pathways, inhibiting the activation of fibroblasts and EMT and the migration of A549 epithelial cells, which alleviated pulmonary fibrosis." (PMID 35172837, 2022). "IL-6 was shown to be upregulated in IPF patients 43 and animal models of pulmonary fibrosis 44; furthermore, JAK2 and STAT3 were increased and activated in the hyperplastic alveolar cells of IPF patients 42, which suggested that IL-6/JAK/STAT3 plays a role in lung fibrosis." (PMID 36147459, 2022). "Interestingly, blockading the PD-1 pathway significantly decreased STAT3, IL-17A, and TGF-β expression levels on Th17 cells, subsequently reducing collagen I production from fibroblasts and attenuating lung fibrosis in a murine model." (PMID 36544757, 2022). "Following bleomycin-induced lung injury, Il11−/− mice are protected from pulmonary fibrosis and exhibit lesser ERK, STAT3 and NF-kB activation, reduced Il1b, Timp1, Ccl2 and diminished IL6 expression, both at baseline and after injury: placing Il11 activity upstream of IL6 in this model." (PMID 34239012, 2021). "STAT3 is part of the JAK/STAT pathway and has a critical role in skin and lung fibrosis." (PMID 34074331, 2021). "The inactivation of SHP2 reduced JAK2-STAT3 signaling and ameliorated dermal and pulmonary fibrosis in mice, suggesting that SHP2 and STAT3 might be molecular checkpoints for tissue fibrosis." (PMID 32708044, 2020).